Y_RNA (Y RNA )
Gene: Miscellaneous RNA gene on chromosome 2 (28,927,243 to 28,927,340, reverse strand). Ensembl gene ENSG00000222224.
Homologues: Orthologues: chimpanzee Y_RNA (100% identical), macaque Y_RNA (90% identical), guinea pig Y_RNA (77% identical), guinea pig Y_RNA (76% identical), guinea pig Y_RNA (74% identical). Paralogues in human: RNY4 (82% identical), RNY4P9 (82% identical), RNY4P6 (81% identical), RNY4P19 (80% identical), RNY4P3 (80% identical), Y_RNA (80% identical), RNY4P14 (79% identical), RNY4P24 (79% identical), RNY4P29 (79% identical), RNY4P7 (79% identical), Y_RNA (79% identical), RNY4P10 (78% identical), and 90 more.